UBASH3A (ubiquitin associated and SH3 domain containing A)
Description:
Interferes with CBL-mediated down-regulation and degradation of receptor-type tyrosine kinases. Promotes accumulation of activated target receptors, such as T-cell receptors, EGFR and PDGFRB, on the cell surface. Exhibits negligible protein tyrosine phosphatase activity at neutral pH. May act as a dominant-negative regulator of UBASH3B-dependent dephosphorylation. May inhibit dynamin-dependent endocytic pathways by functionally sequestering dynamin via its SH3 domain.
Synonyms: CLIP4; STS-2; TULA-1; TULA
Tractability: PROTAC: ubiquitination databases record sites on it; its protein half-life has been measured.
Gene: Protein-coding gene on chromosome 21 (42,403,447 to 42,447,684, forward strand). Ensembl gene ENSG00000160185.
Subcellular location: Cytoplasm; Nucleus
Subcellular location (Human Protein Atlas): Nucleoplasm; Cytosol; Nuclear speckles
Gene Ontology:
Molecular function: protein binding
Biological process: negative regulation of T cell receptor signaling pathway
Cellular component: cytosol; extracellular exosome; nuclear speck; nucleoplasm; cytoplasm; nucleus
Genetic constraint (gnomAD): Loss-of-function variants: 56 observed, 67.39 expected, observed/expected ratio (o/e) 0.83, 90% interval 0.67 to 1.04. The upper end of that interval is the gene's LOEUF score, 1.04, which puts it in group 4 of 6, group 1 being the genes least tolerant of losing a copy. Missense variants: 797 observed, 819.63 expected, observed/expected ratio (o/e) 0.97, 90% interval 0.92 to 1.03. Synonymous variants: 340 observed, 337.44 expected, observed/expected ratio (o/e) 1.01, 90% interval 0.92 to 1.1.
Homologues: Orthologues: chimpanzee UBASH3A (99% identical), macaque UBASH3A (97% identical), dog UBASH3A (81% identical), pig UBASH3A (79% identical), mouse Ubash3a (79% identical), rat Ubash3a (78% identical), guinea pig UBASH3A (76% identical), rabbit UBASH3A (72% identical), Drosophila melanogaster Epp (35% identical), Caenorhabditis elegans T07F12.1 (15% identical). Paralogues in human: UBASH3B (44% identical).
Diseases named in the same sentence as UBASH3A in open-access papers:
UBASH3A is named in the same sentence as 45 diseases in open-access papers, as found by Europe PMC text mining. Sharing a sentence is not in itself a finding about the gene and the disease. The quoted sentences say what the papers report.
type 1 diabetes (14 papers, 2020 to 2024). "Type 1 diabetes-associated variants of the human UBASH3A gene caused higher levels of gene expression and decreased NF-κB signaling and IL2 expression in CD4+ T cells." (PMID 38398001, 2024). "A genetic variant in UBASH3A is linked to type 1 diabetes development in children from the DAISY and BABYDIAB cohorts." (PMID 37224769, 2023). "The type 1 diabetes-associated variants in UBASH3A in human CD4+ T cells resulted in higher levels of gene expression and decreased NF-kB signalling and IL2 expression." (PMID 37224769, 2023). "Among these genes, five (IL6R, RBPJ, SKAP2, SIRPG, UBASH3A) harbour a nearby type 1 diabetes-associated SNP." (PMID 37224769, 2023). "This allele was also reported to abnormally splice UBASH3A transcript in type 1 diabetes patients, thereby reducing UBASH3A protein production." (PMID 36324153, 2022). "UBASH3A is a gene that has been linked to type 1 diabetes and other autoimmune diseases." (PMID 38339213, 2024). "While UBASH3B’s role in autoimmunity appears to be limited, UBASH3A has been associated with several autoimmune diseases, particularly in the regulation of T-cell function in the context of type 1 diabetes, systemic lupus erythematosus, celiac disease, rheumatoid arthritis, and vitiligo." (PMID 38339213, 2024). "Among these genes, Ubash3a was a candidate risk factor in type 1 diabetes." (PMID 37373469, 2023). "Similarly, the potential impact of rs1893592 in UBASH3A has been recognized and is associated with arthritis and type 1 diabetes." (PMID 32211018, 2020). "Non-coding susceptibility alleles within UBASH3A are associated with several autoimmune diseases, including type 1 diabetes and RA, and are also associated with increased transcription, thereby leading to reduced transcription of interleukin-2 (IL2) in effector T cells." (PMID 32117312, 2020). "Therefore, UBASH3A might be involved in mediating the risk of type 1 diabetes by inhibiting T-cell receptor-induced NF-κB signalling." (PMID 38339213, 2024). "Although previous studies revealed the individual effects of UBASH3A on risk for type 1 diabetes (T1D; a common autoimmune disease), the relationship of UBASH3A with other T1D risk factors remains largely unknown." (PMID 37240014, 2023). "Genome-wide association studies and functional studies showed that UBASH3A and its genetic variants contribute to at least five different autoimmune diseases, including type 1 diabetes (T1D), suggesting a broad role of UBASH3A in autoimmunity." (PMID 37240014, 2023). "The overlapping loci included UBASH3A and SH2B3 in type 1 diabetes and celiac disease, and LPP in autoimmune thyroid disease and vitiligo." (PMID 33574239, 2021).
autoimmune disease (11 papers, 2013 to 2025). A disorder resulting from loss of function or tissue destruction of an organ or multiple organs, arising from humoral or cellular immune responses of the individual to their own tissue constituents. "A T-cell ubiquitin ligand coding gene on chromosome 21, SH3 domain-containing protein A (UBASH3A), negatively regulates T-cell signaling and it is a risk gene for autoimmune diseases." (PMID 40155863, 2025). "It is well known that UBASH3A is primarily expressed in T-cells and is associated with autoimmune diseases, whereas UBASH3B is ubiquitously expressed and involved in regulating T-cell receptor signalling and prostate cancer." (PMID 38339213, 2024). "UBASH3A has also been associated with other autoimmune diseases, such as celiac disease and rheumatoid arthritis." (PMID 24367383, 2013). "Regarding to this, the UBASH3a gene seems to be a common genetic factor in autoimmune diseases because different polymorphism of this locus has been associated with autoimmune diseases like T1D, CD, RA and vitiligo." (PMID 23565265, 2013). "Together the functional role of the protein encoded by this gene, the reported data in the eQTLs databases and our results point to the UBASH3a gene as a new element in the pathogenic mechanism of autoimmune diseases." (PMID 23565265, 2013). "Previous studies have indicated whether genetic variants in the UBASH3A gene have been associated with human susceptibility to autoimmune diseases, such as diabetes, rheumatoid arthritis, and systemic lupus erythematosus." (PMID 39452702, 2024). "Thus, UBASH3A plays a broader role in regulating autoimmunity beyond T1D, consistent with its association with other autoimmune diseases in humans." (PMID 32694640, 2020). "This study uncovers novel interactions between two independent autoimmune risk loci, UBASH3A and PTPN22, each of which contribute to multiple distinct autoimmune diseases." (PMID 37240014, 2023). "Finally, it remains to be determined whether the intriguing presence of UBASH3A within the CD6 signalosome provides a molecular basis for the observation that single-nucleotide polymorphisms within both CD6 and UBASH3A genes are associated with autoimmune diseases." (PMID 33125054, 2021). "Moreover, our study indicates that UBASH3a can be considered as a common genetic factor in autoimmune diseases." (PMID 23565265, 2013). "Therefore, analysis of UBASH3a in autoimmune diseases where CD6 acts as a positive regulator of T cell activation may shed light on the pathogenic role of CD6." (PMID 39679790, 2025). "However, it is important to further investigate UBASH3A as a potential therapeutic target due to UBASH3A’s role in autoimmunity through the regulation of T-cell function and the modulation of signalling pathways that are critical in autoimmune diseases." (PMID 38339213, 2024). "In addition, the results of this study may facilitate the development of new combinatorial therapies for autoimmune disease that target both UBASH3A and PTPN22 or the key molecular pathways involving these two risk factors." (PMID 37240014, 2023). "Congruent with our identification of UBASH3A within the CD6 signalosome and the view that CD6 constitutes a promising target for autoimmune disease treatment, single-nucleotide polymorphisms associated with human autoimmune diseases have been found in the Cd6 and Ubash3a genes." (PMID 33125054, 2021). "Furthermore there is a need to determine whether the statistical associations are related with the involvement of UBASH3a in the pathogenesis of SLE and other autoimmune diseases." (PMID 23565265, 2013). "Although UBASH3A has been identified as a potential therapeutic target, there are no clinical trials investigating its use in treating autoimmune diseases." (PMID 38339213, 2024).
autoimmune disease (continued). "These possibilities can be further examined in T cells from healthy subjects and from subjects with autoimmune disease, as well as in mouse models of autoimmune disorders, such as the NOD strain, in which both Ubash3a and Ptpn22 were shown to contribute to the development of T1D." (PMID 37240014, 2023).
Autoimmunity (7 papers, 2011 to 2025). The occurrence of an immune reaction against the organism's own cells or tissues. "In addition to T1D, UBASH3A deficiency also promoted salivary gland inflammation in females, demonstrating its broad impact on autoimmunity." (PMID 32694640, 2020). "UBASH3A is a negative regulator of T cell activation and IL-2 production and plays key roles in autoimmunity." (PMID 37240014, 2023). "The data presented here support an immunomodulatory role for UBASH3A that fine-tunes T cell-mediated autoimmunity." (PMID 32694640, 2020). "Beyond T1D, disruption of Ubash3a in NOD mice increased the degree of salivary gland inflammation in females demonstrating the relevance of Ubash3a in autoimmunity beyond T1D and the first evidence of a possible role in Sjögren syndrome." (PMID 32694640, 2020). "Upon stimulation, T cells from UBASH3A / UBASH3B double deficient mice are hyper-proliferative and produce more IL-2 and IFNγ than wild-type T cells, underscoring the vital role UBASH3A/B in T cell regulation and autoimmunity." (PMID 38461240, 2024). "Thus, UBASH3A deficiency preferentially enhanced female salivary gland inflammation but did not alter lacrimal gland autoimmunity." (PMID 32694640, 2020). "UBASH3A has been shown to regulate T-cell activation and T-cell receptor CD3 complex turnover, contributing to autoimmunity." (PMID 38339213, 2024). "In this review paper, we summarized the current knowledge about UBASH3A and UBASHB in mammalian development, as well as their roles in apoptosis, inflammation, and autoimmunity." (PMID 38339213, 2024). "Despite critical involvement in autoimmunity, the connection between UBASH3A and cancer has not yet been established." (PMID 38461240, 2024). "Of note, disruption of Ubash3a was not sufficient to drive autoimmunity of the normally unaffected organs." (PMID 32694640, 2020).
rheumatoid arthritis (6 papers, 2013 to 2024). A chronic, systemic autoimmune disorder characterized by inflammation in the synovial membranes and articular surfaces. "Diseases associated with certain UBASH3A single nucleotide polymorphisms include rheumatoid arthritis, vitiligo, Graves’ disease, celiac disease, systemic lupus erythematosus, atopic dermatitis, and Addison’s disease." (PMID 38339213, 2024). "The transcription of UBASH3A in rheumatoid arthritis is suppressed via the epigenetic regulation of super-enhancers in CD4+ T-cells." (PMID 38339213, 2024).
diabetes (5 papers, 2020 to 2024). "This and the fact that Cblb is a documented susceptibility gene in diabetic Komeda rats makes Ubash3a a plausible candidate for a T1D susceptibility gene." (PMID 34205929, 2021). "From these and previously reported results, it is likely that the genes encoding UBD, UBASH3A and TCRVβ13a participate in pathways that initiate and lead to diabetes." (PMID 34205929, 2021). "The mechanism of diabetes resistance attributable to UBASH3A is probably related to its role in suppressing T cell activity." (PMID 34205929, 2021). "In this report, we sought to determine if UBASH3A controls diabetes development in NOD mice to support its role in human T1D." (PMID 32694640, 2020).
celiac disease (4 papers, 2011 to 2024). An autoimmune genetic disorder with an unknown pattern of inheritance that primarily affects the digestive tract. "Our current results place the candidate genes SH2B3, CTLA4, BACH2 and UBASH3A at the very heart of the immune response in the pathogenesis of both T1D and celiac disease." (PMID 21829393, 2011). "Lastly, four of the nine TPOA associated SNPs (in SH2B3, CTLA4, BACH2 and UBASH3A) have also been associated with celiac disease (but not the SNPs in RASGRP1, STAT4, PTPN22, IL2 and FCRL3)." (PMID 21829393, 2011).
vitiligo (4 papers, 2013 to 2024). Generalized well circumscribed patches of leukoderma that are generally distributed over symmetric body locations and is due to autoimmune destruction of melanocytes. "Functional prediction of the variants in non-MHC vitiligo loci identified predicted deleterious variants at UBASH3A confer protection from vitiligo." (PMID 26870082, 2016).
Arthritis (3 papers, 2020 to 2023). Inflammation of a joint. "Furthermore, analysis of collagen-induced arthritis in wild-type and Ubash3a-deficient mice showed significantly worse arthritis scores in the null mutants." (PMID 36324153, 2022).
inflammatory bowel disease (3 papers, 2020 to 2023). A spectrum of small and large bowel inflammatory diseases of unknown etiology. "Among these genes, previous studies had reported that FNDC4 (fibronectin type III domain containing 4), RNF186 (ring finger protein 186), and UBASH3A (ubiquitin associated and SH3 domain containing A) were associated with inflammatory bowel disease." (PMID 33043022, 2020).
leukemia (3 papers, 2018 to 2024). A malignant (clonal) hematologic disorder, involving hematopoietic stem cells and characterized by the presence of primitive or atypical myeloid or lymphoid cells in the bone marrow and the blood. "In contrast to solid tumors, the data presented herein suggest an inhibitory role for HSPA1B in leukemia progression, whose expression depend upon the level of UBASH3A and UBASH3B." (PMID 38461240, 2024). "In this study, we show that leukemias expressing high FLI1 produce either higher UBASH3B or lower UBASH3A." (PMID 38461240, 2024). "As FLI1 knockdown blocks leukemia cell proliferation, we next examined impact of UBASH3A and UBASH3B on cell growth." (PMID 38461240, 2024). "The UBASH3A, SF3B1, RUNX1 and ASXL1 mutations gradually appeared and became the major clones at MDS stage, while IDH2 gradually emerged as the dominant clone at leukemia stage." (PMID 36167633, 2022). "The clonal evolution analysis of FA case (P1001) showed the mutations of UBASH3A, SF3B1, RUNX1 and ASXL1 gradually appeared at the later stage of MDS, while the IDH2 alteration become the dominant clone at the leukemia stage." (PMID 36167633, 2022). "The balance between oncogenic and tumor suppressor activity of UBASH3B and UBASH3A, respectively, likely contributes to FLI1-induced leukemia cell proliferation." (PMID 38461240, 2024).
systemic lupus erythematosus (3 papers, 2013 to 2024). An autoimmune multi-organ disease typically associated with vasculopathy and autoantibody production. "The aim of the present study was to determine whether the UBASH3a gene influence the susceptibility to systemic lupus erythematosus (SLE) in Caucasian populations." (PMID 23565265, 2013).
breast carcinoma (2 papers, 2022). "Four potential breast-cancer-predisposing genes, i.e., UBASH3A, MYH13, UTP11L, and PAX7, were selected for further validation through transfection and ectopic expression of wild-type and mutated constructs followed by mass spectrometry profiling and/or Western blot analyses." (PMID 35625741, 2022). "The UBASH3A and MYH13 variants were functionally assessed in MDA-MB-231 and MCF-7 breast cancer cell lines." (PMID 35625741, 2022). "Another report revealed that hypermethylation of genes (LAX1, SIT1, and UBASH3A) leads to enhanced anti-tumor T-cell responses in breast cancer." (PMID 35517856, 2022).
clear cell renal cell carcinoma (2 papers, 2021 to 2024). "In vitro UBASH3A gene knockdown studies on a renal cell carcinoma cell line showed inhibited cell migration and inhibited viability, implying the potential for metastasis induction in clear cell renal cell carcinoma." (PMID 38339213, 2024). "In vitro gene knockdown studies on a renal cell carcinoma cell line concluded that knockdown of UBASH3A inhibited cell migration and viability and therefore could induce metastasis in clear cell renal cell carcinoma." (PMID 34502088, 2021).
head and neck squamous cell carcinoma (2 papers, 2020 to 2024). A squamous cell carcinoma that arises from any of the following anatomic sites: lip and oral cavity, nasal cavity, paranasal sinuses, pharynx, larynx, and salivary glands. "However, higher expression of UBASH3A had a better prognosis outcome in diffuse large B-cell lymphoma, Breast invasive Carcinoma, Colon adenocarcinoma, Head and neck squamous cell carcinoma, Liver hepatocellular carcinoma and Skin cutaneous melanoma." (PMID 38461240, 2024).
sarcoidosis (2 papers, 2025). Sarcoidosis is a multisystemic disorder of unknown cause characterized by the formation of immune granulomas in involved organs. "Among them, there were 14 genes (ABT1, BTN2A2, C2orf74, CCDC88B, FAM213A, MDH2, METTL21B, PRSS16, RP3-473L9.4, TCF19, TSFM, UBASH3A, UQCC2, ZSCAN26) associated with sarcoidosis risk consistently across these tissues." (PMID 40075078, 2025). "In addition, our TWAS pinpointed many tissue-specific sarcoidosis-associated genes and found expressions of 14 genes (ABT1, BTN2A2, C2orf74, CCDC88B, FAM213A, MDH2, METTL21B, PRSS16, RP3-473L9.4, TCF19, TSFM, UBASH3A, UQCC2, ZSCAN26) associated with sarcoidosis across all three target tissues." (PMID 40075078, 2025).
dermatomyositis (1 paper, 2022). Dermatomyositis (DM) is a type of idiopathic inflammatory myopathy characterized by evocative skin lesions and symmetrical proximal muscle weakness. "First, the study included a small number of UBASH3A-stained lymph node samples collected from patients with dermatomyositis as the control group for RA patients." (PMID 36324153, 2022). "Furthermore, double immunofluorescence staining of CD4 and UBASH3A in CD4+ T cells from lymph nodes showed weaker UBASH3A staining in RA patients compared with dermatomyositis patients." (PMID 36324153, 2022).
erythroleukemia (1 paper, 2024). Acute erythroid leukemia characterised by the presence of at least 50% erythroid precursors and at least 20% myeloblasts in the bone marrow. "UBASH3B and UBASH3A are found to act as an oncogene and tumor suppressor, respectively, and their combined effect determines erythroleukemia progression downstream of FLI1." (PMID 38461240, 2024). "FLI1 is shown in this study to promote erythroleukemia progression by inhibiting UBASH3A and expression and inducing UBASH3B expression." (PMID 38461240, 2024). "FLI1 promotes erythroleukemia progression in part by modulating expression of the oncogenic UBASH3B and tumor suppressor UBASH3A." (PMID 38461240, 2024).